ABI2 (abl interactor 2)
Description:
Regulator of actin cytoskeleton dynamics underlying cell motility and adhesion. Functions as a component of the WAVE complex, which activates actin nucleating machinery Arp2/3 to drive lamellipodia formation. Acts as a regulator and substrate of nonreceptor tyrosine kinases ABL1 and ABL2 involved in processes linked to cell growth and differentiation. Positively regulates ABL1-mediated phosphorylation of ENAH, which is required for proper polymerization of nucleated actin filaments at the leading edge. Contributes to the regulation of actin assembly at the tips of neuron projections. In particular, controls dendritic spine morphogenesis and may promote dendritic spine specification toward large mushroom-type spines known as repositories of memory in the brain (By similarity). In hippocampal neurons, may mediate actin-dependent BDNF-NTRK2 early endocytic trafficking that triggers dendrite outgrowth (By similarity). Participates in ocular lens morphogenesis, likely by regulating lamellipodia-driven adherens junction formation at the epithelial cell-secondary lens fiber interface (By similarity). Also required for nascent adherens junction assembly in epithelial cells.
Synonyms: Abi-2; AblBP3; ArgBP1; ARGBPIA; AIP-1; ABI2B; SSH3BP2; AIP1; argBPIB
Tractability: Small molecule: a structure with a bound ligand is known. PROTAC: ubiquitination databases record sites on it; its protein half-life has been measured.
Gene: Protein-coding gene on chromosome 2 (203,328,252 to 203,447,728, forward strand). Ensembl gene ENSG00000138443.
Subcellular location: Cytoplasm; Nucleus; Cell projection, lamellipodium (Isoform 1); Cell projection, filopodium; Cytoplasm, cytoskeleton; Cell junction, adherens junction
Subcellular location (Human Protein Atlas): Nucleoplasm; Cytosol; Vesicles
Pathways (Reactome):
Signal Transduction: RAC1 GTPase cycle; RAC2 GTPase cycle; RAC3 GTPase cycle; RHO GTPases Activate WASPs and WAVEs; VEGFA-VEGFR2 Pathway
Disease: FCGR3A-mediated phagocytosis
Immune System: Regulation of actin dynamics for phagocytic cup formation
Gene Ontology:
Molecular function: identical protein binding; protein binding; signaling adaptor activity; small GTPase binding; ubiquitin protein ligase binding; cytoskeletal anchor activity; kinase binding; SH3 domain binding
Biological process: mitophagy; peptidyl-tyrosine phosphorylation; positive regulation of Arp2/3 complex-mediated actin nucleation; positive regulation of lamellipodium assembly; Rac protein signal transduction; actin polymerization or depolymerization; cell migration; cytoskeleton organization; lens fiber cell morphogenesis; neuron migration; regulation of dendritic spine morphogenesis
Cellular component: cytoplasm; cytosol; filopodium tip; lamellipodium; nucleoplasm; nucleus; SCAR complex; actin-based cell projection; dendritic spine; adherens junction; cytoskeleton; filopodium
Genetic constraint (gnomAD): Loss-of-function variants: 19 observed, 47.69 expected, observed/expected ratio (o/e) 0.4, 90% interval 0.28 to 0.58. The upper end of that interval is the gene's LOEUF score, 0.58, which puts it in group 2 of 6, group 1 being the genes least tolerant of losing a copy. Missense variants: 514 observed, 640.23 expected, observed/expected ratio (o/e) 0.8, 90% interval 0.75 to 0.86. Synonymous variants: 204 observed, 226.13 expected, observed/expected ratio (o/e) 0.9, 90% interval 0.8 to 1.01.
Homologues: Orthologues: pig ABI2 (99% identical), macaque ABI2 (96% identical), chimpanzee ABI2 (95% identical), dog ABI2 (94% identical), tropical clawed frog abi2 (93% identical), mouse Abi2 (87% identical), rat Abi2 (85% identical), guinea pig ABI2 (85% identical), zebrafish abi2b (70% identical), zebrafish abi2a (60% identical). Paralogues in human: ABI1 (66% identical), ABI3 (32% identical).
Diseases named in the same sentence as ABI2 in open-access papers:
ABI2 is named in the same sentence as 25 diseases in open-access papers, as found by Europe PMC text mining. Sharing a sentence is not in itself a finding about the gene and the disease. The quoted sentences say what the papers report.
benign prostate tumors (1 paper, 2023). "Further data mining of the prostate cancer transcriptome atlas (PCTA) database revealed a higher correlation between PIM and ABI2 expression in metastatic castration-resistant PCa than in benign prostate tumors." (PMID 37042842, 2023).
cerebral small vessel disease (1 paper, 2022). Cerebral small vessel disease is the term currently used to pathological processes that affect the brain parenchymal circulation (arterioles, capillaries, and veins). "SNP rs116426890 is intronic to ABI2 and is linked to the expression of CARF, ICA1L, FAM117B, and NBEAL1 which are associated with both white matter hyperintensities and fractional anisotropy, predictors of cerebral small vessel disease which is involved in strokes and vascular dementia." (PMID 36684006, 2022).
ciliopathies (1 paper, 2022). "Mice with a homozygous KO of Abi2 show both eye and male reproductive abnormalities consistent with ciliopathies." (PMID 36456625, 2022). "Histological and morphological evidence of phenotypes found in ciliopathies in knockout mouse lines are presented as examples (genes Abi2, Wdr62, Ap4e1, Dync1li1, and Prkab1)." (PMID 36456625, 2022). "Abi2, Ap4e1, and Prkab1 therefore have strong evidence to be novel candidate ciliopathy genes." (PMID 36456625, 2022). "ABI2 or Abi2 has not been shown to have any association with ciliopathies in humans nor links to retinal abnormalities characteristic of ciliopathies." (PMID 36456625, 2022). "Five of these genes predicted to have ciliary interaction (Abi2, Wdr62, Ap4e1, Dync1li1, and Prkab1) had abnormal morphological features detected by imaging that are consistent with the spectrum of phenotypes observed in ciliopathies." (PMID 36456625, 2022).
glioma (1 paper, 2023). A benign or malignant brain and spinal cord tumor that arises from glial cells (astrocytes, oligodendrocytes, ependymal cells). "High expression of TTN has been reported in gliomas, while ABI2‐deficient mice exhibit difficulties in learning and memory." (PMID 37594177, 2023).
HCMV infection (1 paper, 2014). "The interaction with WAVE2, ABI1, ABI2, NAP1, CYFIP1, and talin-1 were validated in conventional immunoprecipitation experiments when pUL135 was expressed in both isolation and the context of HCMV infection." (PMID 25121749, 2014).
head and neck squamous cell carcinoma (1 paper, 2020). A squamous cell carcinoma that arises from any of the following anatomic sites: lip and oral cavity, nasal cavity, paranasal sinuses, pharynx, larynx, and salivary glands. "Studies have shown that FGFR1 knockout can cause ciliary shortening, IGFR1 plays an important role in ciliary elongation, and ABI2 is a tumor suppressor and a cell migration suppressor, participating in human head and neck squamous cell carcinoma." (PMID 32357862, 2020).
inflammatory bowel disease (1 paper, 2015). A spectrum of small and large bowel inflammatory diseases of unknown etiology. "Consistent with that, another group showed upregulation of the Abi2 gene together with the genes for the fibroblast growth factor, profilin-2, and radixin during tumorigenesis of inflammatory bowel disease- (IBD-) associated CRC." (PMID 26345720, 2015).
Insulin resistance (1 paper, 2019). Increased resistance towards insulin, that is, diminished effectiveness of insulin in reducing blood glucose levels. "Genes downregulated (n = 3) during the first ACTH response were associated with ECM remodeling and insulin resistance (ADAMTS9), cell growth and migration (ABI2), and negative regulation of tyrosine kinase activity (PTPN12)." (PMID 30804370, 2019).
intellectual disabilities (1 paper, 2018). "In addition, rare variants in ABI2 have been found in an exome sequencing study in consanguineous families with intellectual disabilities." (PMID 30147856, 2018).
prostate carcinoma (1 paper, 2023). A carcinoma that arises from epithelial cells of the prostate gland. "PIM1 kinase promotes prostate cancer invasion by directly phosphorylating ABI2, which increases WAVE regulatory complex activity and enhances actin dynamics to drive tumor cell protrusion." (PMID 37042842, 2023).
prostate tumors (1 paper, 2023). "Our data suggest that PIM1 expression, in addition to ABI2, could serve as a potential biomarker to assess the invasive and metastatic potential of primary prostate tumors." (PMID 37042842, 2023).
Retinal dysplasia (1 paper, 2022). Abnormal growth and differentiation, structure and appearance of the retina present from birth. "Retinal dysplasia, as seen in the Abi2 KO mice, has been previously noted in the description of the ocular manifestations of Meckel syndrome." (PMID 36456625, 2022).
tumor (11 papers, 2018 to 2025). "Tumor-cell interaction may explain why the loss of ABI2 impacts tumor growth, as ABI2 knockout has been implicated in reduced matrix adhesion and cell–cell adhesions." (PMID 37042842, 2023). "THRP is 83% homologous to the mouse c-Abl-interacting protein-2 (Abi2), a c-Abl-modulating protein with tumor suppressor activity." (PMID 39851568, 2025). "This protein is 83% homologous to mouse c-Abl-interacting protein-2 (Abi2), a c-Abl-modulating protein with tumor suppressor activity." (PMID 39851568, 2025). "Meanwhile, RNA-seq and IP experiments indicated that ABI2, acting as a crucial factor of tumor suppression, can significantly inhibit PI3K/Akt signaling pathway via the interaction with Rho GTPase RAC1." (PMID 38937761, 2024). "Immunohistochemical (IHC) staining on tumor slices of mouse models indicated that overexpression of BART13-3p significantly reduced the expression of ABI2 in S26-BART13-3p tumors relative to the control tumors." (PMID 31907338, 2020). "A previous study showed that ABI2 functions as a tumor suppressor and a cell migration inhibitor." (PMID 33123477, 2020). "Furthermore, we find that EBV-miR-BART13-3p directly targets ABI2, known as a tumor suppressor and a cell migration inhibitor, drives epithelial-mesenchymal transition (EMT) by activating c-JUN/SLUG signaling pathway." (PMID 31907338, 2020). "Therefore, the enhanced NPC cell invasiveness and tumor metastasis potential resulted from EBV-miR-BART13-3p overexpression are dependent on ABI2 inhibition." (PMID 31907338, 2020). "Studies have shown that ABI2 (Abl-interactor 2 protein) suppresses cell growth, and its truncated form plays a role in the acceleration of tumorigenesis, suggesting that ABI2 may be a tumor suppressor in RB." (PMID 32992741, 2020). "Our findings reveal that phosphorylation by PIM1 increases ABI2 protein stability, which leads to stabilization of the WRC and enhances tumor cell protrusive activity and invasion." (PMID 37042842, 2023). "The specific mechanism has been demonstrated that EBV-miR-BART13-3p directly targets tumor suppressor gene ABI2, which consequently up-regulates the c-JUN/SLUG signaling, eventually leading to epithelial-mesenchymal transformation (EMT) and tumor metastasis." (PMID 31907338, 2020). "By taking the intersection of the target genes predicted by the three databases, we noticed a potential candidate gene, Abl interactor 2 (ABI2), which is known as a cell migration inhibitor and a tumor suppressor." (PMID 31907338, 2020). "There is no clear evidence of a role of ABI2 in tumors, but previous reports suggest that ABI2 functions as a tumor suppressor since ABI2 suppresses cell growth and its truncated form accelerates the tumorigenesis." (PMID 32545553, 2020).
cancer (6 papers, 2019 to 2025). A tumor composed of atypical neoplastic, often pleomorphic cells that invade other tissues. "This analysis revealed that IQGAP1, FLNB, and ACTB are involved in the “Proteoglycans in cancer” pathway, IQGAP1, ABI2, and ACTB are associated with the “Regulation of actin cytoskelet”, IQGAP1 and ACTB are linked to the “Adherens junction”." (PMID 40672380, 2025). "Mechanistically, ABI2 serving as a co-activator of transcriptional factor HHEX upregulated SLC17A9 to promote HCC cancer stem cell-like properties and tumorigenesis." (PMID 38844969, 2024). "We also confirmed the cancer promoting role of very rare helpers, including ABI2, NCOR2 and PAK1 that are altered in 1–4% of EACs." (PMID 31308377, 2019). "ABI2 expression in cancers was significantly lower than that in normal controls." (PMID 33123477, 2020).
infection (4 papers, 2019 to 2024). The state of being infected such as from the introduction of a foreign agent such as serum, vaccine, antigenic substance or organism. "For analysed aba-insensitive mutants (abi1, abi2 and abi5), a reduction in the number of infection sites at 5 dpi, as well as the number of developed females and males, were observed." (PMID 37375924, 2023). "For the abi2 mutant, the infection sites number decreased to 64%, the number of females to 69% and males to 68%." (PMID 37375924, 2023). "To investigate whether ABA signaling can affect immune response after pathogen infection, we compared the expression of PR1 and PDF1.2 genes in Col-0 and ABA insensitive mutants abi1.1, abi2.1 after infection with B. cinerea and Pst DC3000." (PMID 32899695, 2020). "The decreased number of infection sites was found in abi1 (PP2C), abi2 (PP2C) and abi5 (transcription factor) signalling mutants, where an elevated expression of ABI2 and ABI5 genes was shown." (PMID 37375924, 2023). "To answer the question, we performed infection tests on wild type and ABA mutant roots and analysed the expression levels of selected ABA-related genes (ABI1, ABI2, ABI5, PYL5, PYL6, CYP707A1 and CYP707A4) at the early stage of root infection." (PMID 37375924, 2023). "B. subtilis also failed to potentiate the expression of PR1 in abi2.1, while in abi1.1 mutant PR1 was significantly upregulated after infection with Pst DC3000." (PMID 32899695, 2020).
ABI2 also shares sentences with these, for which no sentence is quoted: acute myocardial infarction (1 paper); breast adenocarcinoma (1); breast carcinoma (1); cervical cancer (1); kidney adenocarcinoma (1); nasopharyngeal carcinoma (1); rectal cancer (1); Stroke (1); vascular dementia (1); velocardiofacial syndrome (1).